PLEK (pleckstrin)
Description:
Major protein kinase C substrate of platelets.
Synonyms: p47; PLEK1
Tractability: Antibody: its Gene Ontology location is reachable by antibodies, with high confidence. PROTAC: ubiquitination databases record sites on it; its protein half-life has been measured.
Gene: Protein-coding gene on chromosome 2 (68,365,282 to 68,397,453, forward strand). Ensembl gene ENSG00000115956.
Subcellular location (Human Protein Atlas): Nucleoli
Pathways (Reactome):
Hemostasis: Platelet degranulation
Gene Ontology:
Molecular function: phosphatase activator activity; phosphatidylinositol-3,4-bisphosphate binding; protein binding; protein homodimerization activity; protein kinase C binding
Biological process: actin cytoskeleton organization; cortical actin cytoskeleton organization; hematopoietic progenitor cell differentiation; inositol phosphate metabolic process; integrin-mediated signaling pathway; negative regulation of G protein-coupled receptor signaling pathway; negative regulation of inositol phosphate biosynthetic process; negative regulation of thrombin-activated receptor signaling pathway; phospholipase C-inhibiting G protein-coupled receptor signaling pathway; plasma membrane bounded cell projection assembly; platelet aggregation; platelet degranulation; positive regulation of actin filament bundle assembly; positive regulation of actin filament depolymerization; regulation of cell diameter; ruffle organization; thrombin-activated receptor signaling pathway; negative regulation of calcium-mediated signaling; phospholipase C-activating G protein-coupled receptor signaling pathway; positive regulation of integrin activation; positive regulation of platelet activation; protein secretion by platelet; intracellular signal transduction; positive regulation of cellular component biogenesis
Cellular component: cytoplasm; membrane; ruffle membrane; cytosol; extracellular region; plasma membrane
Genetic constraint (gnomAD): Loss-of-function variants: 14 observed, 27.04 expected, observed/expected ratio (o/e) 0.52, 90% interval 0.34 to 0.81. The upper end of that interval is the gene's LOEUF score, 0.81, which puts it in group 3 of 6, group 1 being the genes least tolerant of losing a copy. Missense variants: 272 observed, 295.61 expected, observed/expected ratio (o/e) 0.92, 90% interval 0.83 to 1.02. Synonymous variants: 97 observed, 106.58 expected, observed/expected ratio (o/e) 0.91, 90% interval 0.77 to 1.08.
Homologues: Orthologues: chimpanzee PLEK (99% identical), macaque PLEK (99% identical), mouse Plek (92% identical), pig PLEK (92% identical), dog PLEK (91% identical), guinea pig PLEK (91% identical), rabbit PLEK (89% identical), rat Plek (89% identical), tropical clawed frog plek (75% identical), zebrafish plek (67% identical). Paralogues in human: PLEK2 (38% identical).
Diseases named in the same sentence as PLEK in open-access papers:
PLEK is named in the same sentence as 68 diseases in open-access papers, as found by Europe PMC text mining. Sharing a sentence is not in itself a finding about the gene and the disease. The quoted sentences say what the papers report.
periodontitis (9 papers, 2015 to 2024). An acute or chronic inflammatory process that affects the tissues that surround and support the teeth. "Notably, associations between pleckstrin and inflammatory diseases like UC, celiac disease, diabetes, RA and periodontitis have been reported, although the underlying pathophysiological mechanisms are unclear." (PMID 35087525, 2021). "Although our results also indicate that pleckstrin is regulated via the MEK3- p38α pathway, further studies are required to elucidate the exact signaling pathways involved in pleckstrin regulation in order to devise future treatment strategies for periodontitis and periodontitis-associated diseases." (PMID 35087525, 2021). "PLEK might be a susceptibility locus for venous thromboembolism, and its expression is increased in UC, periodontitis, and celiac disease." (PMID 33262784, 2020). "Thus, our novel findings of significant differences in salivary levels of pleckstrin between patients with CP and healthy controls implies that this protein could be a non-invasive diagnostic biomarker for periodontitis." (PMID 35087525, 2021). "To date, pleckstrin has been implicated in a range of autoimmune and inflammatory diseases such as rheumatoid arthritis, ulcerative colitis, atherosclerosis, T2DM, periodontitis, and CVD." (PMID 38384322, 2023). "We previously reported that PLEK gene expression is upregulated in the gingival tissues of patients with periodontitis compared to healthy controls, as well as induced in response to LPS treatment in HGFs." (PMID 35087525, 2021). "Only one gene, PLEK, was identified as commonly up-regulated in all four diseases, with fold changes of 1.6 in periodontitis, 1.5 in CVD, 4.1 in RA, and 1.8 in UC." (PMID 26686060, 2015). "Only one gene, pleckstrin (PLEK), was significantly overexpressed in periodontitis, CVD, RA, and UC, implicating this gene as an important networking link between these chronic inflammatory diseases." (PMID 26686060, 2015). "We also report, for the first time, that PLEK is commonly up-regulated in periodontitis and the chronic inflammatory diseases CVD, RA, and UC." (PMID 26686060, 2015). "Studies have been shown that PLEK is significantly over-expressed in periodontitis, cardiovascular disease, rheumatoid arthritis, and ulcerative colitis, and thought to be a crucial mediator in the secretion and activation pathways of pro-inflammatory cytokines TNF-α and IL-1β." (PMID 36258174, 2022). "Using saliva from 169 individuals diagnosed with CP and healthy controls, we investigated whether pleckstrin could serve as a novel biomarker of periodontitis." (PMID 35087525, 2021). "Transcriptomic analysis of periodontitis identified a special upregulated gene, pleckstrin, which was overexpressed in patients with UC and other chronic inflammatory diseases, supporting the hypothesis of a network between periodontitis and IBD." (PMID 34616755, 2021). "Based on our findings identifying PLEK as a commonly up-regulated gene in all four diseases, we further investigated the protein expression of this gene in gingival tissue biopsies from patients with periodontitis and healthy controls." (PMID 26686060, 2015). "In addition, correlation analysis showed that CD53, CYBB, and PLEK were significantly positively linked with activated CD4+T cells in the immune microenvironment of peri‐implantitis, making them effective biomarkers to differentiate it from periodontitis." (PMID 38780047, 2024). "Therefore, we speculated that PLEK might contribute to the periodontitis progression via interacting with IRF-8." (PMID 26334995, 2015). "Moreover, we explored the interlink or sub-cellular localization of pleckstrin with microsomal prostaglandin E synthase-1 (mPGES-1), an important key enzyme of inflammation processes involved in numerous chronic inflammatory diseases including RA, osteoarthritis, and periodontitis." (PMID 35087525, 2021).
periodontitis (continued). "In conclusion, this study identified several genes (CTSS, PLEK, IRF-8, PTGS2 and FOSB) that involved in the development and progression of periodontitis." (PMID 26334995, 2015). "This study identified genes (CTSS, PLEK, IRF-8, PTGS2, and FOSB) that may be involved in the development and progression of periodontitis." (PMID 26334995, 2015).
breast carcinoma (8 papers, 2013 to 2026). "This gene encodes a protein that contains a pleckstrin homology (PH) domain and is a guanine nucleotide exchange factor that upregulates Rho GTPase, which plays an essential role in cell motility, migration, and growth of invasive breast cancer cells." (PMID 32978388, 2020). "Herein, we overcome this hurdle by delivering a mini-obscurin-comprising the obscurin-pleckstrin homology (PH) domain, which is ∼50-times smaller than the full-length protein-into aggressive breast cancer cells via adenovirus and lipid nanoparticles." (PMID 41910118, 2026). "The gain-of-function mutation in the pleckstrin homology domain of AKT1 (AKT1E17K) occurs in lung and breast cancer." (PMID 35681625, 2022). "The single hotspot mutation in the pleckstrin homology domain of the AKT1 gene [G49A:E17K] has been described in human breast, colon, and ovarian cancers, with the highest incidence observed in breast cancer." (PMID 27515171, 2016). "We have performed biochemical and functional characterization of six novel AKT1 pleckstrin homology domain mutants that have been identified predominantly in human breast cancers." (PMID 23237847, 2013). "Additionally, OSBPL3 shows an enhanced phosphorylation level at S426, S251, and S273 loci within the pleckstrin homology domain in multiple tumors, such as breast cancer or lung adenocarcinoma." (PMID 34738015, 2021). "We have performed functional analysis of six non-hotspot AKT1 pleckstrin homology domain mutants identified in recent large-scale breast cancer sequencing studies." (PMID 23237847, 2013).
celiac disease (6 papers, 2016 to 2024). An autoimmune genetic disorder with an unknown pattern of inheritance that primarily affects the digestive tract. "PLEK has biased expression in lymph node and has been evidenced to be able to cause Celiac disease." (PMID 30072632, 2018). "study on patients with UC and celiac disease, autoimmune diseases, found PLEK expression to be upregulated in tissue biopsies from the colon and rectum." (PMID 35087525, 2021). "We found 54 single-nucleotide polymorphisms (SNPs) in 5 genes associated with celiac disease (TAGAP, IL18R1, RGS21, PLEK, and CCR9) in time to celiac disease analyses (10−4>P>5.8x10−6)." (PMID 27015091, 2016). "On the other hand, association evidence for RGS21, IL18R1, PLEK, CCR9, TAGAP was only found for celiac disease." (PMID 27015091, 2016). "However, confirmatory evidence (p<10−4) was found for SNPs in five regions previously reported to be associated with celiac disease (TAGAP, IL18R1, RGS21, PLEK, and CCR9)." (PMID 27015091, 2016).
atherosclerosis (5 papers, 2015 to 2024). A disease characterized by the build-up of fatty material and calcium deposition in the arterial wall resulting in partial or complete occlusion of the arterial lumen. "To provide targeted diagnostic assistance for atherosclerosis patients, we constructed a proprietary Nomogram model based on the expression of PLEK, IRF8, BTK, CCR1, and CD68." (PMID 38716195, 2024). "To further investigate the potential role of gut microbiota-associated core macrophage genes in atherosclerosis, we applied unsupervised clustering methods based on the expression of PLEK, IRF8, BTK, CCR1, and CD68 to classify atherosclerosis patients into groups A and B." (PMID 38716195, 2024). "We stimulated RAW264.7 cells and PLEK-knockdown RAW264.7 cells with LPS and TNF-α to observe whether PLEK would influence the atherosclerosis process through the NFκB signaling pathway." (PMID 38716195, 2024). "Gut microbiota-associated macrophage genes (PLEK, IRF8, CD68, CCR1, and BTK) may be implicated in the pathogenesis of atherosclerotic plaques and could serve as diagnostic markers to aid patients with atherosclerosis." (PMID 38716195, 2024). "Leveraging machine learning algorithms, we have identified PLEK, IRF8, BTK, CCR1, and CD68 as evaluative markers to assist in the diagnosis of atherosclerosis." (PMID 38716195, 2024). "These six hub genes, TYROBP, ITGAM, ITGB2, CD86, PLEK, LCP2 may be important biomarkers for the progression of atherosclerosis and potential treatment targets." (PMID 38382092, 2024).
COVID-19 (5 papers, 2021 to 2024). A disease caused by infection with severe acute respiratory syndrome coronavirus 2. "PLEK and LCP2 genes which code proteins, pleckstrin and lymphocyte cytosolic protein 2, respectively, may play a role in COVID-19 pathogenesis." (PMID 36510222, 2022). "The differential expression analysis identified six differentially expressed genes (DEGs) shared by myasthenia gravis (MG) and COVID-19, namely SAMD9, PLEK, GZMB, JUNB, NR4A1, and NR1D1." (PMID 38384322, 2023). "In the present study, we identified six shared genes (SAMD9, PLEK, GZMB, JUNB, NR4A1, and NR1D1) of MG and COVID-19 patients through bioinformatic analysis." (PMID 38384322, 2023). "However, in patients with COVID-19, the expression of ITGAM, vWF, and PLEK was higher when compared with ECs of healthy patients." (PMID 39066212, 2024).
lung carcinoma (5 papers, 2014 to 2023). "PLEK gene expression was previously found to be associated with poor prognosis and chemoresistance in lung cancer patients." (PMID 36969247, 2023). "The hotspot AKT1E17K mutation in the pleckstrin homology domain of AKT1 occurs in approximately 0.6–2% of human lung cancers." (PMID 26859676, 2016). "In lung cancer a somatic mutation in the pleckstrin homology (PH) domain of AKT1 that results in glutamic acid to lysine substitution at residue 17 (E17K) was reported with overall frequency of 0.6–2%." (PMID 26859676, 2016). "The hotspot E17K mutation in the pleckstrin homology domain of AKT1 occurs in approximately 0.6–2% of human lung cancers." (PMID 26053093, 2015). "Again, we found that a low expression of the PLEK gene was associated with poor survival rates in lung cancer patients (P = 0.02)." (PMID 25360158, 2014). "There is currently a lack of research on the relationship between EVI2B, SASH3, and PLEK with lung cancer." (PMID 34234827, 2021). "Interestingly, one previous study found that PLEK was negatively correlated with the purity of lung cancer tissue, and low expression of PLEK led to high tumor purity, low immune score, low CD8+ T lymphocyte content, and shorter 5-year survival." (PMID 36969247, 2023).
ovarian carcinoma (5 papers, 2008 to 2020). A malignant neoplasm originating from the surface ovarian epithelium. "AKT1 activation has been reported in gastric, prostate cancer and somatic mutation in pleckstrin homology domain (PHD) of AKT1 was reported in human breast, colorectal and ovarian cancers." (PMID 28881811, 2017). "A recurrent somatic mutation, E17K, in the pleckstrin homology domain of the AKT1 gene, has been recently described in breast, colorectal, and ovarian cancers." (PMID 18611285, 2008). "The Glu17Lys mutation seen in the binding site of AKT3 in kidney cancer was also found in the pleckstrin homology domain of AKT1 in breast, colorectal and ovarian cancers, and results in the activation of AKT1, followed by downstream signaling and cell transformation." (PMID 24362839, 2014).
rheumatoid arthritis (5 papers, 2021 to 2024). A chronic, systemic autoimmune disorder characterized by inflammation in the synovial membranes and articular surfaces. "Studies have reported a significant upregulation of PLEK in ulcerative colitis and rheumatoid arthritis." (PMID 38716195, 2024). "We previously reported the pleckstrin gene (PLEK) to be highly upregulated in gingival tissue of patients with CP and the only gene concurrently upregulated in other inflammatory diseases including rheumatoid arthritis and cardiovascular diseases." (PMID 35087525, 2021). "However, there is evidence suggesting that PLEK might have a significant impact on chronic inflammatory conditions like CVD, rheumatoid arthritis (RA), and ulcerative colitis (UC)." (PMID 38382092, 2024).
asthma (3 papers, 2017 to 2022). "PLEK is a major substrate for protein kinase C signaling, a pathway strongly implicated in asthma pathogenesis was upregulated in severe asthmatics and exhibited a moderate ability to distinguish between severe and mild-moderate asthmatics." (PMID 35600600, 2022).
colon cancer (3 papers, 2014 to 2025). "Building from our approach, we identified four new putative cancer genes (RWDD1, NCF1, PLEK, and VAV3), whose expression profiles were found to be associated with poor survival rates in melanoma, lung, or colon cancer patients." (PMID 25360158, 2014). "To demonstrate the potential value of our approach, we identified four putative cancer genes (RWDD1, NCF1, PLEK, and VAV3), whose expression was associated with poor survival rates in melanoma, lung, or colon cancer patients." (PMID 25360158, 2014). "Finally, the pleckstrin homology‐like domain in family A (PHLDA1) has implications for intestinal tumorigenesis, as demonstrated by siRNA‐mediated suppression of PHLDA1 in colon cancer cells." (PMID 40013338, 2025). "In particular, digestive organ cancer cell lines, such as 58As9 (scirrhous cancer), CaCO2 and HT-29 (colon cancer) expressed the full-length PLEKHN1, and we could ignore the non-specific band by comparison of PLEKHN1-knockout-HT-29 (hereafter, PLEK-KO cells) and the parental HT-29 cells." (PMID 29531808, 2018).
epilepsy (3 papers, 2019 to 2022). A brain disorder characterized by episodes of abnormally increased neuronal discharge resulting in transient episodes of sensory or motor neurological dysfunction, or psychic dysfunction. "In summary, severe phenotypes, such as early-onset epilepsy in infancy, occur in male patients with a missense mutation in specific domains (e.g., pleckstrin homology and IQ calmodulin-binding motif domains)." (PMID 36267700, 2022). "Still, they did have severe phenotypes, such as early-onset epilepsy in infancy, because the mutations were located in domains like the pleckstrin homology and IQ calmodulin-binding motif domains." (PMID 36267700, 2022). "Patients carrying pathogenic variants in the pleckstrin homology domain exhibited milder phenotypes without epilepsy." (PMID 31920647, 2019). "In addition, patients 31 and 32, carrying pathogenic variants in the pleckstrin homology domain exhibited milder phenotypes without epilepsy." (PMID 31920647, 2019). "The end of the stalk region contains the globular tail/pleckstrin homology domain, which recognizes vesicles and membranous organelles Thus far, limited studies have investigated the role of KIF1A in the origin of epilepsy." (PMID 32174959, 2020).
lung adenocarcinoma (3 papers, 2014 to 2023). A carcinoma that arises from the lung and is characterized by the presence of malignant glandular epithelial cells. "We found that two genes in lung adenocarcinoma had enriched mutations in their pocket regions: CRP (P = 4.9 × 10-7) and PLEK (P = 2.1 × 10-3)." (PMID 25360158, 2014).
Obesity (3 papers, 2022 to 2025). Accumulation of substantial excess body fat. "Considering the well-established association between obesity and PCOS, the potential effects of the XIST- hsa-miR-146a-5p- PLEK axis on PCOS characteristics merit further investigation." (PMID 38486041, 2024).
autoimmune disease (2 papers, 2021). A disorder resulting from loss of function or tissue destruction of an organ or multiple organs, arising from humoral or cellular immune responses of the individual to their own tissue constituents. "Eleven proteins (increased: ATP5B, CALML5, COLEC11, FCGBP, PLEK, PLXND1; decreased: APOB, ATP8B1, FAM20C, LOXL3, TIMD4) were significantly altered in bvFTD with autoimmune disease compared to those without autoimmune disease." (PMID 34539672, 2021).
B-cell lymphoma (2 papers, 2007 to 2021). "ARHGEF3 contains the diffuse B-cell lymphoma homology and pleckstrin homology domains but lacks similarity with other known functional domains." (PMID 35174167, 2021). "In general, a pleckstrin homology (PH) domain follows the DH (diffuse B-cell lymphoma homology) domain and this tandem DH-PH module is the signature motif of the Dbl family of guanine nucleotide exchange factors (GEFs)." (PMID 17584488, 2007).